NGF (nerve growth factor)
Diseases named in the same sentence as NGF in open-access papers (continued):
Sharing a sentence is not in itself a finding about the gene and the disease.
non-small cell lung carcinoma (6 papers, 2021 to 2026). A group of at least three distinct histological types of lung cancer, including non-small cell squamous cell carcinoma, adenocarcinoma, and large cell carcinoma. "In contrast, chaenomester D, a natural anti-inflammatory oxylipin, not only promotes NGF secretion but also inhibits the proliferation of non-small cell lung cancer (NSCLC) cells." (PMID 40783715, 2025). "NGF promotes neural infiltration in non-small cell lung cancer (NSCLC), while 5-hydroxytryptamine (5-HT), which is secreted by nerves, is markedly increased in tumors exhibiting extensive neural invasion." (PMID 41163091, 2025). "Nerve growth factor (NGF) secretion from non-small cell lung cancer(NSCLC) cells promotes neuronal differentiation and axon formation within the TME." (PMID 39897050, 2025). "Furthermore, in a series of histologically different non-small cell lung cancers, the expression of TrkA and NGF was mainly documented in squamous cell carcinomas and to a lesser extent in adenocarcinomas." (PMID 36289793, 2022). "NGF boosts angiogenesis in tumor tissue, including non-small cell lung cancers (NSCLCs)." (PMID 34502019, 2021).
osteoporosis (6 papers, 2018 to 2025). A condition of reduced bone mass, with decreased cortical thickness and a decrease in the number and size of the trabeculae of cancellous bone (but normal chemical composition), resulting in increased fracture incidence. "Studies have shown that bone marrow and serum levels of NGF are significantly elevated in patients with osteoporosis and negatively correlate with bone mineral density (BMD)." (PMID 40860871, 2025). "The direct role of NGF in osteoporosis treatment is unclear, and future studies should focus on how NGF affects bone metabolism through neuromodulation and explore its synergistic effects with existing anti-osteoporosis drugs." (PMID 40860871, 2025). "Ovariectomy- and sham-operated mice were injected with an anti-NGF antibody (10 mg/kg, intraperitoneally, administered 2×, 14 days apart), and the effect on behavioural indices of osteoporosis-related pain and on sensory neuron plasticity was evaluated." (PMID 29922744, 2018). "This discovery suggests that altering the interaction between NGF and its receptors, as seen in female mice with hR100E-NGF, could potentially provide therapeutic benefits for managing chronic pain and preventing osteoporosis." (PMID 39324959, 2024). "Taken together, these data suggest that anti-NGF antibodies may be useful in the treatment of prefracture hypersensitivity that is reported in 10% of patients with osteoporosis." (PMID 29922744, 2018). "Here, we demonstrate anti-NGF efficacy in the OVX mouse model of osteoporosis-related pain." (PMID 29922744, 2018). "This is the first report to demonstrate efficacy of anti-NGF therapy in an osteoporosis model." (PMID 29922744, 2018). "The aim of this study was to examine the efficacy of anti-NGF antibody therapy against cutaneous hypersensitivity, deep musculoskeletal pain, and physical function in a mouse model of OVX-induced osteoporosis." (PMID 29922744, 2018).
pulmonary fibrosis (6 papers, 2010 to 2026). Chronic progressive interstitial lung disorder characterized by the replacement of the lung tissue by connective tissue, leading to progressive dyspnea, respiratory failure, or right heart failure. "In this study, nerve growth factor (NGF) and IL were observed, and it was speculated that they might be related with pulmonary fibrosis." (PMID 33193637, 2020). "Although enhanced dermal levels of NGF reflect skin involvement in SSc, previous data and the present study suggest that increased serum NGF levels do not reflect skin or pulmonary fibrosis in SSc." (PMID 21085492, 2010).
ulcer (6 papers, 2008 to 2025). "Correct indications and prompt treatment with rh-NGF promote healing of persistent epithelial defects and induce healing of ulcers and recovery of the corneal sensitivity." (PMID 39040985, 2024). "The restoration of the corneal thickness and the healing of PED and ulcers after the treatment of rh-NGF confirm the crucial role of NGF in promoting the release of factors involved in the maintenance of the integrity of the corneal epithelium and ocular surface hemostasis." (PMID 39040985, 2024). "About this we hypothesized that in ulcers the rh-NGF promotes better stromal healing with restore of the corneal thickness that induces the faster epithelial resurfacing as compared to PED." (PMID 35707524, 2022). "Importantly, local administration of NGF protein to the GU sites in rats accelerated ulcer healing, increased angiogenesis, and improved the quality of mucosal regeneration." (PMID 34440733, 2021). "Our studies also showed that NGF expression is reduced in vivo in gastric endothelial cells of aging rats, and local NGF therapy of GUs in aging rats increases angiogenesis, accelerates ulcer healing, and improves mucosal regeneration in ulcer scars." (PMID 34440733, 2021). "Furthermore, we did not assess the presence and expression of the corresponding receptor, TrkC, or the receptors for other neurotrophic factors (TrkA for NGF, TrkB for BDNF) in the ulcer tissue." (PMID 39550735, 2025).
anhidrosis (5 papers, 2012 to 2024). Lack of sweating or the ability to sweat when provoked by the appropriate stimulus. "CIP with Anhidrosis (CIPA) is the most common type of CIP, which is caused mainly by mutations in NTRK1 and NGF genes, and is characterized by mental retardation and the inability to sweat (Anhidrosis)." (PMID 37248554, 2023). "Interestingly, intramuscular injections of NGF are able to induce neuronal sensitization in rats and some mutations in TrkA result in congenital insensitivity to pain with anhidrosis (CIPA), an autosomal recessive disorder characterized by the inability to feel pain and absence of sweating." (PMID 35837121, 2022). "Patients with CIPA exhibited insensitivity to pain, anhidrosis, and recurrent fever as they lack NGF‐dependent primary afferents and sympathetic postganglionic neurons crucial for pain sensation and homeostasis maintenance." (PMID 38581121, 2024). "Hereditary sensory and autonomic neuropathy type 4 (HSAN4), also known as congenital insensitivity to pain with anhidrosis (CIPA), is a rare genetic disorder caused by NTRK1 gene mutations, affecting nerve growth factor signaling." (PMID 38133079, 2023). "Moreover, a newly identified loss of function NGF mutation also results in a lack of nociception and anhidrosis, whereas a second NGF mutation, which causes a lack of nociception without anhidrosis, is proposed to be hypofunctional." (PMID 22528859, 2012).
Arrhythmia (5 papers, 2008 to 2025). Any cardiac rhythm other than the normal sinus rhythm. "We next examined the functional implications of sitagliptin-attenuated resistin secretion, and found that resistin played an important role in sympathetic innervation and arrhythmias through modulation of NGF levels." (PMID 26811539, 2016). "Our results suggest that the mechanisms of sitagliptin-induced anti-arrhythmias were related to an attenuated NGF expression through a resistin-dependent pathway, and that the resistin expression was coupled to the regulation of GIP." (PMID 26811539, 2016). "Research suggests an increase in post-MI systemic NGF results in a retrograde transport of NGF to LSG which triggers nerve sprouting and sympathetic hyperinnervation—creating an environment for arrhythmia." (PMID 21876659, 2008). "Since it is not known whether LXFG has beneficial effects on arrhythmia following MI, the present study sought to provide evidence on this topic, by focusing on sympathetic remodeling and the NGF/TrKA/PI3K/AKT signaling pathway." (PMID 34221073, 2021).
bladder cancer (5 papers, 2016 to 2026). "Here, we identify nerve growth factor (NGF) as the driver of ILC2 pro-tumoral functions in patients with bladder cancer." (PMID 41723132, 2026). "Therefore, we analyzed the anesthesia effect of propofol, its impact on serum NGF, S100B protein levels, and immune functions in patients who received bladder cancer surgery." (PMID 36072772, 2022).
cardiac arrest (5 papers, 2023 to 2025). Cessation of breathing and/or cardiac function. "More recently, the same Authors extended their experience with intranasal NGF by treating a small cohort of children in vegetative state after out-of-hospital cardiac arrest, and children with post-traumatic unresponsive wakefulness syndrome." (PMID 40153582, 2024). "Recently, promising results have also been reported by the combined treatment of intranasal human-recombinant NGF (hr-NGF) and transcranial direct current stimulation (tDCS) in 3 children with chronic vegetative state after out-of-hospital cardiac arrest." (PMID 37789391, 2023). "In humans, intranasal delivery of NGF has been recently investigated both in a child with severe TBI and in 3 children with chronic vegetative state secondary to prolonged out-hospital cardiac arrest, with a significant improvement both of their cognitive and motor functions after the treatment." (PMID 37789391, 2023).
cervical carcinoma (5 papers, 2021 to 2025). A carcinoma arising from either the exocervical squamous epithelium or the endocervical glandular epithelium. "Neurotrophins, such as BDNF and NGF, are overexpressed in tumor cells in cervical cancer, and HIV infection is associated with the upregulation of neurotrophin expression." (PMID 37445902, 2023). "Nerve growth factor (NGF) is increasingly implicated in cervical cancer progression, but its mechanism in cervical cancer is unclear." (PMID 34722240, 2021). "The involvement of neurotrophic factors in the developmental mechanism of CIPN has not yet been well identified and still remains controversial; despite this, reduced levels of the BDNF family member NGF were found to be associated with CIPN development in patients with cervical carcinoma." (PMID 33920318, 2021). "NGF induces CC cell proliferation and migration, and high levels of NGF and TrkA are associated with PNI in early-stage cervical cancer." (PMID 40003544, 2025). "In this study, the stimulation of NGF led to cervical cancer cell proliferation and migration and promoted the transcription of YAP target genes." (PMID 34722240, 2021). "Our results provide the first direct evidence of NGF/TrkA crosslinking with Hippo signaling pathways in cervical cancer." (PMID 34722240, 2021). "By observing tumor volume and weight in the nude mice model, it was found that NGF subcutaneous injection significantly promoted the formation of subcutaneous tumors of cervical cancer cells." (PMID 34722240, 2021). "In this study, we found the role of the NGF signaling in cervical cancer and its relationship with the Hippo pathway." (PMID 34722240, 2021). "Our study indicates that combined targeting of the NGF signaling and the Hippo pathway represents a novel therapeutic strategy for treatment of cervical cancer." (PMID 34722240, 2021). "Here, studies demonstrate that NGF inhibits the Hippo signaling pathway and activates Yes-associated protein (YAP) to induce cervical cancer cell proliferation and migration." (PMID 34722240, 2021). "Taken together, these data provide the first direct evidence of crosstalk between the NGF signaling and Hippo cancer pathways, an interaction that affects cervical cancer progression." (PMID 34722240, 2021). "To explore the biological function of NGF in cervical cancer cells, we investigated the effect of NGF on HeLa and C-33A cell lines at certain concentration (200 ng/ml)." (PMID 34722240, 2021). "Our results confirmed that NGF was critical for the proliferation and metastasis of cervical cancer cells and increases cervical cancer progression by inhibiting Hippo signaling." (PMID 34722240, 2021). "NGF can induce the proliferation and migration of cervical cancer cells." (PMID 39061654, 2024). "Although studies indicate that exosomes secreted by cervical cancer cells induce their own innervation, it remains unclear whether NGF is packaged within exosomes or is required for exosome-mediated neurite outgrowth." (PMID 39061654, 2024). "Furthermore, preliminary data have linked the expression of neurotrophins, in particular NGF, to the presence of perineural invasion (PNI) in certain tumors, including also one study investigating this relationship in patients with cervical cancer." (PMID 37445902, 2023). "Information regarding the NGF/TrkA potential role in the progression of cervical cancer remains unclear." (PMID 34722240, 2021). "The emerging data have shown that NGF/TrkA are overexpressed in cervical squamous cell carcinoma, but very low levels in normal tissues, which are correlated with the initiation, progression, and prognosis of cervical cancer." (PMID 34722240, 2021). "Cervical cancer cells were maintained in serum-free medium for 24 h prior to treatment with NGF." (PMID 34722240, 2021). "NGF may function as a mediator of cervical cancer progression by modulating Hippo/YAP pathway." (PMID 34722240, 2021).
cervical carcinoma (continued). "Samples from Loop Electrosurgical Excision Procedure (LEEP) for suspected cervical cancer were obtained, and immunohistochemistry was performed to evaluate BDNF and NGF expression." (PMID 37445902, 2023). "This study demonstrated that high NGF and TrkA expression, but not p75NRT expression, is associated with PNI in cervical cancer, further highlighting the possible role of neurotrophin modulation in the progression of cervical cancer." (PMID 37445902, 2023).
chronic obstructive pulmonary disease (5 papers, 2006 to 2025). A chronic and progressive lung disorder characterized by the loss of elasticity of the bronchial tree and the air sacs, destruction of the air sacs wall, thickening of the bronchial wall, and mucous accumulation in the bronchial tree. "This study explored the roles of fibroblast growth factor (FGF) and nerve growth factor (NGF) in chronic obstructive pulmonary disease (COPD) exacerbations, highlighting significant findings with potential clinical implications." (PMID 41226620, 2025). "It is interesting to note that NT-3 expression, but not NGF or BDNF expression, is transcriptionally downregulated in chronic obstructive pulmonary disease, suggesting that cells from the airways may be poor at producing NT-3 compared to other neurotrophins." (PMID 16441896, 2006).
corneal diseases (5 papers, 2014 to 2022). "All these evidences underlined an important role of NGF in corneal physiopathology, and also suggested that NGF might exert therapeutic action in a wide spectrum of corneal diseases." (PMID 31889912, 2019). "Understanding the effects of NGF on the stem cells of the cornea (limbal stem cells [LSCs]) will lead to better treatments for debilitating corneal diseases." (PMID 30599086, 2019). "Clinical trials are ongoing to evaluate therapy with NGF eye drops in corneal diseases and first results seem to be very promising." (PMID 26504592, 2015). "Nerve growth factor (NGF) alteration in corneal diseases has been largely evaluated; NGF pathway alteration has been tested in an animal model by demonstrating NGF to be involved in corneal healing and in sensory denervation." (PMID 26504592, 2015). "Other preclinical and clinical studies have investigated the contribution of NGF to corneal disease." (PMID 25383879, 2014). "Consistently, the current study also demonstrated the suppressive role of NGF on HSK related ROS generation, implicating that the underlying mechanisms of NGF on treating these three common corneal diseases might be partially overlapped." (PMID 31889912, 2019). "Moreover, in studies evaluating human being, low tears level of NGF has been proved to be reduced in eyes affected by dry eye and has been proved to be effective in several corneal diseases such as neurotrophic keratitis, immune corneal ulcer, and HSV keratitis and after cataract surgery." (PMID 26504592, 2015). "Despite its efficacy in the treatment of neurotrophic ulcers and its potential in the treatment of several other corneal diseases including LSCD, the role of NGF in the maintenance of LSCs remains poorly understood." (PMID 30599086, 2019).
diabetic nephropathy (5 papers, 2013 to 2025). "Therefore, we propose the scientific hypothesis: The CDK5 activity in diabetic nephropathy causes podocyte injury and apoptosis by regulating the NGF/Sirt1 axis and oxidative stress inflammatory factors in podocytes." (PMID 35874807, 2022). "An increase in NGF expression under high glucose conditions can lead to renal diseases such as diabetic nephropathy." (PMID 39080783, 2024). "Prior studies showed that serum and tear NGF levels were higher in DR patients and correlated well with HbA1c, severity of hyperglycemia, progression of the disease, and the existence of diabetic nephropathy." (PMID 26807305, 2015). "Our analyses suggest the involvement of NGF (Nerve Growth Factor, a prototypical Central Nervous System trophic molecule) in diabetic nephropathy." (PMID 23358711, 2013). "In addition, inhibition of Cdk5 overactivation in our diabetic nephropathy model positively regulated the NGF/Sirt1 axis and reduced the HG-induced oxidative stress response and apoptosis in podocytes." (PMID 41181709, 2025).
Headache (5 papers, 2006 to 2024). Cephalgia, or pain sensed in various parts of the head, not confined to the area of distribution of any nerve. "The same research group also demonstrated that CSF levels of NGF positively correlate with headache frequency, in line with our current study findings, but do not correlate with VAS scores representative of headache severity." (PMID 34991456, 2022). "The differential upregulation of P2X3 and TRPV1 receptors in culture by NGF begged the question whether other mediators believed to be involved in headache might elicit similar long-lasting changes." (PMID 16566843, 2006). "Other markers also differed between groups, but most significantly between patients with worsened (TGF-ß1: 60 pg/ml, VEGF: 328 pg/ml, ß-NGF: 6 pg/ml) as compared to unchanged headaches (TGF-ß1: 29 pg/ml, VEGF: 183 pg/ml, ß-NGF: 3 pg/ml)." (PMID 38890625, 2024). "The New Daily Persistent Headache Biomarkers Study investigates the CGRP levels and nerve growth factor levels in patients with NDPH and patients with CM compared with healthy volunteers." (PMID 35861031, 2022). "Repeated intramuscular injections of NGF in healthy subjects caused an increase in mechanical sensitivity for the masseter muscle but not for the temporalis muscle; nevertheless, both referred pain frequency and number of headache days were not increased following NGF injections." (PMID 37569811, 2023). "We were not able to find any study in the literature assessing the correlation between headache frequency and levels of in vivo PGE2 and VEGF, and we found only two studies that evaluated the correlation between CSF levels (not serum) of NGF and BDNF and number of headache days." (PMID 34991456, 2022).